YAP1 (Yes1 associated transcriptional regulator)
Diseases named in the same sentence as YAP1 in open-access papers (continued):
Sharing a sentence is not in itself a finding about the gene and the disease.
head and neck squamous cell carcinoma (26 papers, 2017 to 2025). A squamous cell carcinoma that arises from any of the following anatomic sites: lip and oral cavity, nasal cavity, paranasal sinuses, pharynx, larynx, and salivary glands. "Given the role of YAP1 signaling in cancer cell stemness, depletion of PIPKIγi5 enhances YAP1 signaling and promotes tumorsphere formation in head and neck squamous cell carcinoma." (PMID 40784457, 2025). "In head and neck squamous cell carcinoma cells, Egfr regulates the activation of Yap1 via Mob1 phosphorylation and inactivation." (PMID 37107231, 2023). "The FAT1 alterations occur in 29.8% of head and neck squamous cell carcinoma (HNSCC), and FAT1 functional loss results in YAP1 activation." (PMID 33420124, 2021). "By focusing on head and neck squamous cell carcinoma (HNSCC), which displays frequent FAT1 alterations (29.8%), we provide evidence that FAT1 functional loss results in YAP1 activation." (PMID 29985391, 2018). "YAP1 is a key promoter of head and neck squamous cell carcinoma." (PMID 40066231, 2025). "To provide more supporting evidence that YAP1 and FAPα induce an immunosuppressive T cell phenotype, we interrogated the Cancer Genome Atlas (TCGA) database for correlations between YAP1/FAPα expression and immune regulatory molecules in head-and-neck squamous cell carcinoma." (PMID 35986369, 2022). "In head and neck squamous cell carcinoma (HNSCC), BRD4 interacts with the YAP1/TAZ/TEAD transcriptional complex to facilitate expression of oncogenes." (PMID 37994501, 2023). "TIMER2.0 was used to analyze whether YAP1/VEGFC signaling pathway is involved in lymphangiogenesis in head and neck squamous cell carcinoma (HNSCC)." (PMID 37974224, 2023). "Similarly, knockdown of PIPKIγi5, but not PIPKIγi2, in another head and neck squamous cell carcinoma cell line, UM-SCC-1, also significantly increased both the mRNA and protein levels of YAP1 target genes." (PMID 40784457, 2025).
meningioma (26 papers, 2018 to 2026). A generally slow growing tumor attached to the dura mater. "According to European Association of Neuro-Oncology (EANO) guidelines, YAP1 fusion can be an oncogenic driver for sporadic pediatric meningiomas." (PMID 36463108, 2022). "Subsequently YAP1 was found to express in all grades of meningiomas and its deletion caused impaired cell proliferation and migration in vitro, whereas overexpression translates to proliferation and anchorage independent cell growth." (PMID 29558515, 2018). "YAP1 is a transcriptional coactivator of cell growth that is regulated by the Hippo signaling pathway and is especially associated with pediatric Nf2 wild-type meningiomas." (PMID 37898750, 2023). "Meningiomas in infants and toddlers are exceedingly uncommon, and the presence of a YAP1::LMO1-rearranged atypical meningioma in a 16-month-old patient in our cohort further illustrates the distinctive clinical and molecular features seen in this age group." (PMID 41526775, 2026). "Exploratory biomarkers include hippo/YAP activity signatures, which are enriched in NF2- and YAP1-driven meningiomas." (PMID 41487565, 2025). "Rare pediatric meningiomas have been recently identified to have YAP1::MAML2, YAP1::PYGO1, or YAP1::LMO1 gene fusions." (PMID 40491864, 2024). "Around half of all meningiomas harbor inactivating mutations in NF2, leading to deregulation of oncogenic YAP1 activity." (PMID 39380691, 2024). "The oncogenic functions of these YAP1 fusions fundamentally rely on their ability to exert deregulated YAP activity, and YAP1 fusion-positive human meningiomas resemble NF2 mutant meningiomas by both gene expression and DNA methylation-based classification." (PMID 38571886, 2024). "The importance of deregulated YAP activity in the pathobiology of NF2 mutant meningioma is furthermore emphasized by the presence of recurrent YAP1 gene fusions (most frequently YAP1-MAML2) in around 10% of pediatric NF2 wild-type meningiomas." (PMID 38571886, 2024). "The only study that reported solid growth in almost 100% of the cases was based on constitutively activated YAP1, but meningiomas initiated by YAP1 fusion are a rare subset of childhood and young adulthood meningiomas." (PMID 37898750, 2023). "Further research has shown that the YAP1 fusion NF2 wild-type meningiomas exhibit high YAP1 activity and express a similar gene profile as NF2 mutant meningiomas." (PMID 37628996, 2023). "Nonetheless, as more cases of YAP1 fusion meningiomas are identified and analyzed, it becomes evident that certain subtypes, such as YAP1-FAM118B fusion, exhibit distinct biological characteristics from the NF2 mutant." (PMID 37628996, 2023). "This suggests that YAP1 fusion meningiomas represent a spectrum of complex molecular and histopathological profiles." (PMID 37628996, 2023). "YAP1-MAML2 positive meningiomas have been reported to exhibit similarities to NF2 mutant meningiomas, showing an elevated level of YAP1 signaling and a comparable response to a specific group of pharmaceutical reagents." (PMID 37628996, 2023). "Pediatric meningioma with the fusion of YAP1 and MAML2 genes is more likely to have pathological features of rhabdiod cells, which needs to be validated in large-scale studies for exploring better treatment under the integrated diagnosis." (PMID 36463108, 2022). "We report a case of a YAP1-fusion-positive atypical meningioma in a young child and compare it with the previous ones reported." (PMID 36292056, 2022). "Recently, YAP1-fusions have been identified for the first time as potential NF2-independent oncogenic drivers in the development of meningiomas in pediatric patients." (PMID 36292056, 2022). "YAP1 fusion was identified as a potential oncogenic driver in meningiomas by strengthening the deregulation of the Hippo pathway." (PMID 36463108, 2022). "Overexpression of YAP1 has been observed in medulloblastomas, meningiomas, ependymomas, astrocytomas, oligodendrogliomas, and GBMs." (PMID 34012965, 2021).
meningioma (continued). "Additionally, it has been shown that aggressive NF2 mutant meningiomas downregulate oncogenic YAP1 signaling." (PMID 40936721, 2025). "It is currently unknown if low- and high-grade NF2 mutant meningiomas equally rely on YAP1 signaling for their growth and/or survival and would be susceptible to targeted therapy against YAP1." (PMID 38571886, 2024). "Another study found an enrichment of YAP1 fusions in pediatric NF2 wild-type meningiomas." (PMID 38571886, 2024). "Indeed, high levels of YAP1 were found to have nuclear localization in meningiomas, and targeting YAP1 activity was shown to be a potential treatment option in meningiomas." (PMID 38001599, 2023). "A nuclear localization sequence (NLS)-2SA-YAP1 lesion—which constitutively activated YAP1 to inactivate Nf2—was explored to determine whether it would suffice to produce meningioma-like tumors." (PMID 37898750, 2023). "Consequently, hyperactive YAP1 promotes tumor cell proliferation and invasion and plays an oncogenic role in meningioma tumorigenesis." (PMID 37628996, 2023). "Recent studies have indicated that YAP1 activation is frequently associated with the loss of function of the potent tumor suppressor NF2/Merlin, which drives tumor growth, invasion, and resistance to apoptosis in various tumors, including meningioma." (PMID 37628996, 2023). "More recently, YAP1 fusions have been reported in a subset of pediatric meningiomas." (PMID 37628996, 2023). "Extending the clinico-pathological features of YAP1-fused meningiomas, we suggest additional clues for diagnosis and emphasize the urgent need for an integrated multilayered diagnostic approach, combining data from histological and molecular analyses, neuroradiology, and clinical findings." (PMID 36292056, 2022). "Pediatric meningioma with YAP1 fusion is a rare subset of meningiomas." (PMID 36463108, 2022). "Interestingly, loss of function mutations in the tumor suppressor protein NF2 result in increased YAP1 expression and nuclear localization, leading to development of Schwannomas and meningiomas." (PMID 34012965, 2021). "YAP1 fusions have been recently reported among pediatric meningiomas." (PMID 34495383, 2021). "Gene expression-based clustering analyses of YAP1 point mutations have revealed that YAP1 fusion meningiomas resemble low-grade NF2 mutant meningiomas based on the up-regulated genes, whereas, based on the down-regulated genes, YAP1 fusion meningiomas cluster with high-grade NF2 mutant meningiomas." (PMID 37628996, 2023). "However, the number of reported YAP1 fusion meningioma cases remains limited." (PMID 37628996, 2023). "Recently it was reported that some pediatric meningiomas may carry YAP1 fusions." (PMID 34495383, 2021). "YAP1-fusion–positive, NF2-wild-type meningiomas represent a unique pediatric subset with biology that differs from the NF2-driven tumors more commonly observed in older children and adults." (PMID 41526775, 2026). "Hyperactive YAP1, a consequence of the YAP1 fusion protein binding to the TEA domain, leads to tumor cell proliferation and invasion, playing an oncogenic role in meningioma tumorigenesis." (PMID 39202270, 2024). "Many gene fusions are oncogenic, and gene fusions have been reported in meningiomas, particularly NF2 structural rearrangements in radiation-induced meningiomas, and YAP1 fusions in rare pediatric meningiomas." (PMID 38509407, 2024). "Studies have demonstrated that blocking the interaction between YAP1 and TEAD or targeting TEAD auto-palmitoylation can effectively inhibit tumor formation and suppress tumor growth in the YAP1 fusion/NF2 mutant meningioma and schwannoma." (PMID 37628996, 2023). "Analysis with IPA revealed that these drugs target signal cascades potentially relevant in pathogenesis of meningiomas, particular examples are the effect on ERK by trazodone, MAP kinases by emetine, and YAP-1 protein by verteporfin." (PMID 29558515, 2018).
meningioma (continued). "Loss or functional inactivation of NF2 or other upstream Hippo Pathway mediators lead to deregulation and deinhibition of YAP1 and NF2 mutant meningiomas and/or cell lines express high levels of YAP activity and upregulate the expression of several canonical YAP1 targets (such as CTGF and CYR61)." (PMID 38571886, 2024). "YAP1 fusion meningiomas resemble low-grade NF2 mutant meningiomas; based on their upregulated genes and their downregulated genes, they resemble high-grade NF2 mutant meningiomas." (PMID 39202270, 2024). "Alterations to YAP1 have been reported in 9 paediatric meningiomas, specifically sporadic cases lacking in NF2 alterations." (PMID 39612013, 2024). "Our report expands the spectrum of oncogenic YAP1 gene fusions an alternative to NF2 inactivation to include sporadic schwannoma, analogous to what has recently been described in NF2-wildtype pediatric meningiomas." (PMID 35986430, 2022). "Similarly, constitutive activation of YAP1 or the presence of YAP1-MAML2, a fusion protein that was identified in several meningioma patients, can drive the formation of tumors that resemble NF2 mutant meningiomas." (PMID 38001599, 2023). "Interestingly, none of the other meningioma subtypes with characteristic alterations, e.g. mutations in NF2, TRAF7/KLF4 or BAP1, or YAP1 fusion, seem to form epigenetic clusters that are distinct to the same extent." (PMID 33319313, 2021).
pancreatic ductal adenocarcinoma (26 papers, 2012 to 2026). An infiltrating adenocarcinoma that arises from the epithelial cells of the pancreas. "The prognostic value of the miR-141/YAP1 pathway was also proved by analyzing the association between miR-141 expression and clinical outcomes in pancreatic ductal adenocarcinoma patients." (PMID 36624516, 2023). "Furthermore, USP10 desensitizes pancreatic ductal adenocarcinoma (PDAC) cells to NK cell-mediated cytotoxicity by deubiquitinating yes-associated protein 1 (YAP1, a core component of Hippo signaling) to transcriptionally upregulate both PD-L1 and galectin-9 (Gal-9)." (PMID 38715050, 2024). "Recent studies have demonstrated that HIF1α and YAP1 can establish a positive feedback loop, contributing to epithelial-to-mesenchymal transition in pancreatic ductal adenocarcinoma." (PMID 38602536, 2024). "LncRNA PWAR6 regulates proliferation and migration by epigenetically silencing YAP1 in tumorigenesis of pancreatic ductal adenocarcinoma." (PMID 35280814, 2022). "A recent study identified YAP1 as essential KRAS effector in the development of pancreatic ductal adenocarcinoma." (PMID 26716514, 2016). "KRAS mutation could induce LIF expression in human pancreatic ductal adenocarcinoma (PDAC) cells, and LIF inhibits the intracellular Hippo pathway and promotes tumorigenesis by facilitating YAP/TAZ-TEAD interaction and up-regulating the expression of the YAP1 target genes CNTF and ANKRAD." (PMID 35740622, 2022). "Interestingly, metaplastic ducts in chronic pancreatitis, PanINs, and pancreatic ductal adenocarcinoma (PDAC) showed a clear co-expression of PAF1 and YAP1." (PMID 36180487, 2022). "Furthermore, YAP1 and TAZ are robustly activated in adult human pancreatic ductal adenocarcinoma (PDAC) and chronic pancreatitis, and YAP1 is required for progression of PDAC." (PMID 31323030, 2019). "Moreover, a previous study reports that YAP1’s transcriptional activity is modulated by oncogenic KRAS signaling through the MAPK pathway in pancreatic ductal adenocarcinoma without changing its subcellular location." (PMID 38730733, 2024).
triple-negative breast carcinoma (25 papers, 2017 to 2025). An invasive breast carcinoma which is negative for expression of estrogen receptor (ER), progesterone receptor (PR), and human epidermal growth factor receptor 2 (HER2). "The results of this study highlight the potential role of epigenetic regulation of ADIPOQ, GAS5, GATA4, and YAP1 in the molecular pathology of triple-negative breast cancer." (PMID 41226688, 2025). "This phosphorylation is essential for the regulation of DUB3-mediated deubiquitination and stabilization of YAP1, and potentially other oncogenic substrates such as Snail1 in triple-negative breast cancer." (PMID 39827153, 2025). "Among patients with triple-negative breast cancer, 2 out of 9 patients (22.2%) exhibited YAP1 positivity (p = 0.001)." (PMID 40731926, 2025). "A previous study analyzed the nuclear expression of YAP1 in triple-negative breast cancer (TNBC) and showed that adverse prognosis was associated with nuclear YAP1 expression." (PMID 36291755, 2022). "Taken together, these findings provide insights into the transcriptional regulation axis of HJURP/YAP1/NDRG1 in triple-negative breast cancer progression and therapeutic response." (PMID 35459269, 2022). "The impact of YAP1 expression on survival was also evaluated in patients with triple negative breast cancer (TNBC)." (PMID 33718163, 2021). "For example, YAP1 could mediate DTX resistance in triple-negative breast cancer and its decreased expression could enhance the cytotoxicity of DTX and reverse drug resistance." (PMID 37243787, 2023). "In addition, YAP1 activation prevents cell apoptosis of urothelial cell carcinomas after irradiation-induced DNA damage, and YAP1 inhibition radio-sensitizes triple negative breast cancer cells by disrupting the DNA damage response and cell survival pathways." (PMID 34689211, 2022). "Activation of YAP1 could mediate Epithelial-to-Mesenchymal transition in Triple-Negative Breast Cancer." (PMID 35237592, 2022). "However, the role of YAP1 in radioresistance in triple-negative breast cancer (TNBC) is currently unknown." (PMID 29228705, 2017). "In our previous study with triple-negative breast cancer (TNBC), YAP1 activation was correlated with a poor clinical outcome." (PMID 37894401, 2023). "Here, we revealed that Hippo signaling effector YAP1 functioned as a key downstream regulator of LIN28 to modulate the cancer stem cell (CSC)-like properties and tumor progressions in triple negative breast cancer (TNBC)." (PMID 35102250, 2022). "In patients with triple-negative breast cancer (TNBC), high nuclear YAP1 expression was an independent significant determinant of poor DMFS (HR 2.384, 95% CIs 1.055–5.386, P = 0.0367)." (PMID 33718163, 2021). "Here, we identified a YAP1 tyrosine phosphorylation-dependent YAP1-KLF5 oncogenic module, as the key downstream mediator of SRC kinase regulating cancer stemness and metastasis in triple-negative breast cancer (TNBC)." (PMID 36633714, 2023). "And HJURP/YAP1/NDRG1 axis could affect cell proliferation and chemotherapy sensitivity in triple-negative breast cancer." (PMID 35459269, 2022). "Therefore, our research mainly focuses on exploring the progression of triple-negative breast cancer and determines the important role of the HJURP/YAP1/NDRG1 transcriptional regulation axis in triple-negative breast cancer." (PMID 35459269, 2022).